NPAS2 (neuronal PAS domain protein 2)
Diseases named in the same sentence as NPAS2 in open-access papers (continued):
Sharing a sentence is not in itself a finding about the gene and the disease.
non-Hodgkin lymphoma (6 papers, 2014 to 2024). Distinct from Hodgkin lymphoma both morphologically and biologically, non-Hodgkin lymphoma (NHL) is characterized by the absence of Reed-Sternberg cells, can occur at any age, and usually presents as a localized or generalized lymphadenopathy associated with fever and weight loss. "The genetic variation in functional polymorphisms of the circadian genes Cry2 and Ala394Thr in Neuronal PAS domain protein 2 (NPAS2) increases genetic susceptibility to non-Hodgkin's lymphoma." (PMID 39012661, 2024). "Differential NPAS2 expression has been associated with patient outcomes in tumors, lung tumors, non-Hodgkin's lymphoma, and other diseases, and nucleotide variants in the NPAS2 gene were related to cancer patients' outcomes." (PMID 35880088, 2022).
bipolar disorder (5 papers, 2009 to 2024). A disorder of the brain that causes unusual shifts in mood, energy, activity levels and the ability to carry out day-to-day tasks. "The variants are in the Npas2, Cp, Polr3c, Smarca4, Trpv1, and Slc5a7 genes, and many of these genes’ products are in pathways implicated in human bipolar disorders." (PMID 29768498, 2018). "In addition, other clock genes were associated with these psychiatric disorders, such as Npas2 (winter depression, autism spectrum disorder and schizophrenia), RORA and RORB (bipolar disorder) or Tim, Dbp and Ck1ε (autism spectrum disorder)." (PMID 28468274, 2017).
leukemia (5 papers, 2021 to 2025). A malignant (clonal) hematologic disorder, involving hematopoietic stem cells and characterized by the presence of primitive or atypical myeloid or lymphoid cells in the bone marrow and the blood. "Furthermore, not only was CLOCK observed to have altered regulation in leukemias, but its analogue, the NPAS2 gene, was also found to be overexpressed in AML." (PMID 40700255, 2025). "Thus, the overexpression of NPAS2 is present in different types of cancer, indicating that the same mechanism could also occur in leukemia." (PMID 35897788, 2022). "Moreover, NPAS2, CKIε, and SHARP1 were upregulated in leukemia, but their expression was limited to one or two subtypes of leukemia." (PMID 35897788, 2022).
liver cancer (5 papers, 2021 to 2022). An epithelial or non-epithelial malignant neoplasm that arises from the liver. "To explore the expression levels of genes (CSNK1D, CSNK1E, and NPAS2) in liver cancer, we compared the mRNA expression levels of tumor and normal tissues." (PMID 34149816, 2021). "Clinicopathological analysis showed that the expression of NPAS2 in liver cancer correlated with tumor size, TNM stage and distant metastasis." (PMID 34460437, 2021). "We found that higher expression levels of CSNK1D, CSNK1E, and NPAS2 were significantly related to shorter OS of liver cancer patients." (PMID 34149816, 2021). "Additionally, in the liver cancer cell experiment, similar results were obtained, in which the CSNK1D, CSNK1E, and NPAS2 mRNA expression levels were strongly upregulated compared with those in normal liver cells." (PMID 34149816, 2021).
liver fibrosis (5 papers, 2021 to 2025). "Beyond its role in circadian regulation, NPAS2 has also been implicated in promoting liver fibrosis through its regulation of Hes1 expression." (PMID 41007411, 2025). "NPAS2-deficient fibroblasts expedite skin wound healing and dermal collagen reconstruction, and NPAS2 promotes liver fibrosis via direct transcriptional activation of Hes1 in hepatic stellate cells." (PMID 34040522, 2021). "In addition to wound healing and tumorigenesis, dysregulation of NPAS2 is associated with the occurrence of pulmonary fibrosis, hepatic fibrosis and atrial fibrosis." (PMID 40548841, 2025). "Interestingly, previous studies revealed that dysregulation of NPAS2 contributed to liver fibrosis." (PMID 40548841, 2025).
ovarian carcinoma (5 papers, 2015 to 2022). A malignant neoplasm originating from the surface ovarian epithelium. "A GWAS and a replication study for epithelial ovarian cancer (EOC) analyzed variants of several circadian genes (ARNTL, CRY2, CSNK1E, NPAS2, PER3, REV1, and TIMELESS) and two transcription factors (KLF10 and SENP3)." (PMID 30873119, 2019). "Nevertheless, an alternative study has evaluated polymorphism association in nine circadian clock-related genes (ARNTL, CKIE, CLOCK, CRY1-2, CSNKIE, NPAS2, and PER1-3), but however, it did fail finding any association between genes of the circadian rhythm pathway and ovarian cancer." (PMID 30873119, 2019). "The goal of the current study was to examine single nucleotide polymorphisms (SNPs) in circadian genes BMAL1, CRY2, CSNK1E, NPAS2, PER3, REV1 and TIMELESS and downstream transcription factors KLF10 and SENP3 as predictors of risk of epithelial ovarian cancer (EOC) and histopathologic subtypes." (PMID 26807442, 2015). "We further evaluated the correlations between PER1 and these 10 interacting proteins based on the GEPIA database and found that the expression of PER1 in ovarian cancer was correlated with that of ARNTL, CLOCK, CRY1, CRY2, CSNK1D, CSNK1E, NPAS2, and PER3." (PMID 34220965, 2021).
autism (4 papers, 2010 to 2025). Persistent deficits in social interaction and communication and interaction as well as a markedly restricted repertoire of activity and interest as well as repetitive patterns of behavior. "GRIK2 has also been linked to schizophrenia and autism, while NPAS2 is associated with circadian rhythm control." (PMID 40564862, 2025). "Three polymorphisms of interest were highlighted: two SNPs in GRIK2, a gene implicated in a number of neurological maladies such as autism and schizophrenia and an SNP within the NPAS2 gene, which is a putative circadian clock gene." (PMID 26859813, 2016). "NPAS2 plays a regulatory role in acquiring specific types of memory, linking NPAS2 to autistic disorder." (PMID 37807632, 2023). "The thalamo‐cortico‐amygdala pathway, essential for complex emotional memory, has been reported as dysfunctional in autism, these studies on neuronal PAS domain protein 2 (NPAS2) reveal that NPAS2‐deficient mice subjected to behavioral tests exhibit deficits in the long‐term memory." (PMID 37807632, 2023). "In addition, NPAS2 is a close analog of CLOCK and its polymorphisms have earlier been associated with autism, a disorder characterized among others with impaired social interaction and communication." (PMID 20368993, 2010). "Moreover, a study on the hypothesis that clock genes are implicated in autistic disorder revealed noteworthy associations in the PER1 and NPAS2 genes." (PMID 37807632, 2023).
diabetes (4 papers, 2012 to 2024). "For instance, IGFBP2, NPAS2, NDUFS7, and TGM2 showed differential expression in α cells from individuals with T2D and have previously been shown to affect diabetes and islet-related phenotypes or mitochondrial function." (PMID 36656641, 2023). "A list of 15 known clock genes from the primary (Arntl, Clock, Npas2, Per1, Per2, Per3, Cry1, Cry2), secondary (Nrd1d1, Nr1d2, Rora, Rorb, Rorc), and accessory TTFL loops (Nfil3, Dbp) were selected to investigate the effect of diabetes on their rhythmic expression." (PMID 38039846, 2024).
melanoma (4 papers, 2020 to 2023). A malignant, usually aggressive tumor composed of atypical, neoplastic melanocytes. "In melanoma patients, homozygosity of an allele with nine repeats (9/9) was more prevalent, suggesting a role for NPAS2 variants in melanoma susceptibility." (PMID 37887064, 2023). "Sequencing of the putative promoter and 5′ untranslated region of the NPAS2 promoter in patients suffering from melanoma identified several variants." (PMID 37887064, 2023). "Only one study addressed the issue on genetic variability of the promoter region of the NPAS2 clock gene and melanoma risk, and found a significant association with a polymorphic GGC repeat." (PMID 33549124, 2021). "The variant copies of the GGC repeat sequence in the NPAS2 clock gene likely led to the tumorigenesis of melanoma." (PMID 33679872, 2020).
mood disorder (4 papers, 2015 to 2023). A cognitive disorder a disturbance in which the person's mood is hypothesized to be the main underlying feature. "Moreover, the exact role that NPAS2 variants play in mood disorders vulnerability will need to be further examined, and may pave the way for personalized circadian therapy in the management of mental health." (PMID 25989161, 2015). "The circadian rhythm compartments such as Per, Arntl, or Npas2 genes are thought to be closely related to mood disorders." (PMID 31404163, 2019). "Individuals with mood disorders experience perturbations in a myriad of rhythmic processes, therefore, this result was surprising in that we had hypothesized that chronic stress would decrease or completely disrupt Npas2 gene expression rhythms." (PMID 29163035, 2017).
Azoospermia (3 papers, 2018 to 2024). Absence of any measurable level of sperm,whereby spermatozoa cannot be observed even after centrifugation of the semen pellet. "For example, a homozygous mutation in Npas2 has been reported in a Turkish family with nonobstructive azoospermia." (PMID 39834701, 2024). "Further bioinformatics mining revealed that related clock genes (PER1, PER2, CRY2, NR1D1 and NPAS2) were down-regulated in non-obstructive azoospermia patients." (PMID 35910569, 2022). "Current examples are TEX15 and NPAS2 in non-obstructive azoospermia and ADGRG2 in obstructive azoospermia." (PMID 29527098, 2018).
gastric cancer (3 papers, 2022 to 2023). A primary or metastatic malignant neoplasm involving the stomach. "In the setting of gastric cancer, NPAS2 expression levels were evaluated by tissue microarray immunohistochemistry for in situ protein expression analysis in tumor tissue compared to matched adjacent non-tumorous mucosa." (PMID 37887064, 2023). "Taken together, these findings revealed that the radiotherapy or chemotherapy promoted the expression of DNA repair genes (APLF, EID3, EME2, NPAS2 and POLN) of gastric cancer non-stem stem cells to trigger DNA repair, resulting in the biogenesis of GCSCs." (PMID 36153608, 2022).
lung adenocarcinoma (3 papers, 2023 to 2024). A carcinoma that arises from the lung and is characterized by the presence of malignant glandular epithelial cells. "A boxplot was utilized to visually depict the marked upregulation of NPAS2 in tumor tissues of lung adenocarcinoma in comparison to the adjacent paracancerous tissues from the TCGA LUAD dataset." (PMID 38291048, 2024). "In this regard, NPAS2 was identified as a component of a four-chromatin-regulator hub (CBX7, HMGA2, NPAS2 and PRC1) allowing risk stratification and outcome prediction in lung adenocarcinoma patients." (PMID 37887064, 2023). "In addition, we observed that silencing NPAS2 led to enhanced sensitivity of lung adenocarcinoma cells to cisplatin and inhibition of DNA damage repair." (PMID 38291048, 2024). "Accordingly, NPAS2 was included in a five-gene signature (DKK1, CCL20, NPAS2, GNPNAT1 and MELTF) predicting poor prognosis and decreased immunotherapy response in lung adenocarcinoma patients." (PMID 37887064, 2023).
Miscarriage (3 papers, 2013 to 2023). A pregnancy that ends at a stage in which the fetus is incapable of surviving on its own, defined as the spontaneous loss of a fetus before the 22th week of pregnancy. "Genetic variants in the circadian genes ARNTL and NPAS2 are thought to contribute to fertility, with genetic variants in the ARNTL gene being closely related to a higher number of miscarriages and specific genotypes of the Npas2 gene being associated with a reduced number of miscarriages." (PMID 37006462, 2023).
nasopharyngeal carcinoma (3 papers, 2017 to 2023). A carcinoma arising from the nasopharyngeal epithelium. "RNA-seq and miRNA-omics analysis performed in radio-resistant nasopharyngeal cancer (NPC) cells pinpointed the NPAS2–miR-20a-5p axis as crucially involved in NPC radio-resistance and this role was corroborated by experiments with down- or up-regulation of their levels in NPC cell lines." (PMID 37887064, 2023). "MiR-20a-5p reduces the sensitivity of nasopharyngeal carcinoma cells to radiotherapy by targeting NPAS2 and Rab27B, and miR-193a-3p enhances the anti-radiation ability of NPC by targeting SRSF2 43-45." (PMID 32328201, 2020).
rheumatoid arthritis (3 papers, 2015 to 2021). A chronic, systemic autoimmune disorder characterized by inflammation in the synovial membranes and articular surfaces. "Strikingly, ARNTL2 and NPAS2 were the core clock genes that were found to be disturbed in rheumatoid arthritis and they accompanied DEC2 by also reacting to TNF with increased expression." (PMID 30210560, 2017). "Since TNF induces the expression of ARNTL2 and NPAS2, and they are the most disturbed genes in rheumatoid arthritis patients, we investigated how they regulate canonical E-box element compared to more studied ARNTL/NPAS2 complex." (PMID 30210560, 2017). "The expression of clock genes ARNTL2, NPAS2 and DEC2 are disturbed in rheumatoid arthritis, an autoimmune disease with circadian variation of symptoms." (PMID 30210560, 2017). "Patients with rheumatoid arthritis (RA) have altered circadian rhythm of circulating serum cortisol, melatonin and IL-6, as well as disturbance in the expression of clock genes ARNTL2 and NPAS2." (PMID 26710124, 2015).
schizophrenia (3 papers, 2016 to 2025). A major psychotic disorder characterized by abnormalities in the perception or expression of reality. "Indeed, compared with healthy controls, schizophrenia patients presented disruptions in diurnal rhythms of the expression of Per1, Per3, and Npas2, accompanied by a delayed phase in the expression of Per2 and by a decreasing in Per3 and Npas2 expression." (PMID 28468274, 2017).
anaplastic thyroid carcinoma (2 papers, 2023). "NPAS2 was overexpressed in anaplastic thyroid carcinoma and facilitated malignant progression." (PMID 37120564, 2023). "Additionally, in anaplastic thyroid carcinoma NPAS2 was found to be significantly up-regulated in tumor tissue and in vitro experiments showed that NPAS2 silencing in anaplastic thyroid carcinoma cell lines successfully obstructed cell proliferation, migration and invasion." (PMID 37887064, 2023).
bladder cancer (2 papers, 2021 to 2023). "In summary, our work identifies unique epigenomic signatures and 3D genome structures in luminal and basal urinary bladder cancers and suggests a novel link between the circadian transcription factor NPAS2 and a clinical bladder cancer subtype." (PMID 33858483, 2021). "Our work highlights the relevance of epigenetic modifications, open chromatin accessibility, and TF repertoire and identifies a novel identified basic helix loop helix (bHLH) TF NPAS2, all of which cooperate in the coordination of subtype-specific gene expression in bladder cancer." (PMID 33858483, 2021). "Finally, we identify a novel clinically relevant transcription factor, Neuronal PAS Domain Protein 2 (NPAS2), in luminal bladder cancers that regulates other subtype-specific genes and influences cancer cell proliferation and migration." (PMID 33858483, 2021).
breast tumor (2 papers, 2018 to 2024). "In contrast, CLOCK, NPAS2, CIART/CHRONO, BHLHE40, RORA, and RORC were significantly up-regulated in these breast tumors." (PMID 38319971, 2024).
cognitive deficits (2 papers, 2017 to 2025). "In summary we have shown using a mouse model that hepatic NPAS2 may play a role in cognitive impairment consequent to constant light in females." (PMID 40069567, 2025). "This suggests that potential cognitive impairment in constant light conditions may be sex-dependent, and further, that hepatic NPAS2 deletion attenuates this impairment." (PMID 40069567, 2025). "As a result, four SNPs, including the RORA-rs13329238, NPAS2-rs17655330, CLOCK-rs3749473, and RORB-rs10781247 SNPs individually and interactively alters the hazard of cognitive deficits in terms of MMSE scores for normal aging." (PMID 29209239, 2017).
colitis (2 papers, 2022 to 2023). Inflammation of the colon. "On the contrary, we found that in colorectal stromal cells, colitis was associated with decreases in the mRNA levels of Arntl, Clock, Cry1, Cry2, Per2, Per3, Nr1d1, Npas2, and BBR restored the expression of these genes except Per2." (PMID 36528592, 2022). "Examination of C57BL/6 mice with DSS-induced colitis revealed significantly reduced Cry1, Per2, Npas2 and Rev-erbα expression, but significantly increased expression of Rorα." (PMID 37218867, 2023). "We also compared the expression of several key circadian genes including Arntl, Clock, Cry1, Cry2, Per1, Per2, Per3, Nr1d1, and Npas2 in colon samples collected at 03, 09, 15, and 21 of normal mice, colitis mice, normal mice receiving BBR, and colitis mice receiving BBR." (PMID 36528592, 2022).
endometrial cancer (2 papers, 2022 to 2025). Primary or metastatic malignant neoplasm involving the endometrium (mucous membrane that lines the endometrial cavity). "In endometrial cancer of the uterus, the circadian gene NPAS2 operates as a potential tumor stimulator." (PMID 35880088, 2022).
neuroblastoma (2 papers, 2007 to 2022). Neuroblastoma (NB) is the most common solid, extracranial childhood tumor. "Interestingly, addition of lactate to neuroblastoma cells stimulates NPAS2/BMAL1 activity but its release only showed a rhythmicity in response to BMAL1 knockdown in human bone osteosarcoma epithelial cells (U2OS) cells." (PMID 35387328, 2022). "Although ldha has a canonical E-box and has been shown to be activated by both NPAS2 and CLOCK in a neuroblastoma cell line, mRNA levels of this gene were surprisingly stable across time-of-day, experimental condition, and genetic background." (PMID 17945005, 2007).
Stroke (2 papers, 2020 to 2023). Sudden impairment of blood flow to a part of the brain due to occlusion or rupture of an artery to the brain. "The role of NPAS2 as a gas-responsive transcription factor was explored in a mouse model of subarachnoid hemorrhage (SAH), which is characterized by a time-qualified pattern of stroke incidence that was replicated through blood injection in subarachnoid spaces at different circadian time points." (PMID 37887064, 2023).
thyroid carcinoma (2 papers, 2023). "Therefore, if it were consistently found in the reviewed studies that BMAL1, CLOCK and NPAS2 were upregulated in thyroid carcinoma, the suppressors of activity of BMAL1, CLOCK and NPAS2 (CRYs, DECs, and PERs) would be expected to be downregulated in this carcinoma." (PMID 37489438, 2023).